EPM2AIP1 (EPM2A interacting protein 1)
Synonyms: KIAA0766; FLJ11207
Tractability: PROTAC: ubiquitination databases record sites on it; its protein half-life has been measured.
Gene: Protein-coding gene on chromosome 3 (36,985,043 to 36,993,131, reverse strand). Ensembl gene ENSG00000178567.
Subcellular location: Endoplasmic reticulum
Gene Ontology:
Molecular function: identical protein binding; protein binding
Biological process: positive regulation of glycogen biosynthetic process
Cellular component: cytoplasm; cytoplasmic side of endoplasmic reticulum membrane; endoplasmic reticulum; nucleus
Genetic constraint (gnomAD): Loss-of-function variants: 23 observed, 47.17 expected, observed/expected ratio (o/e) 0.49, 90% interval 0.35 to 0.69. The upper end of that interval is the gene's LOEUF score, 0.69, which puts it in group 2 of 6, group 1 being the genes least tolerant of losing a copy. Missense variants: 652 observed, 786.81 expected, observed/expected ratio (o/e) 0.83, 90% interval 0.78 to 0.88. Synonymous variants: 311 observed, 304.05 expected, observed/expected ratio (o/e) 1.02, 90% interval 0.93 to 1.12.
Homologues: Orthologues: chimpanzee EPM2AIP1 (99% identical), dog EPM2AIP1 (91% identical), macaque EPM2AIP1 (91% identical), rabbit EPM2AIP1 (90% identical), guinea pig EPM2AIP1 (90% identical), mouse Epm2aip1 (89% identical), rat Epm2aip1 (89% identical), pig EPM2AIP1 (88% identical). Paralogues in human: SCAND3 (22% identical), ZBED5 (21% identical), ZBED11 (19% identical), ZBED8L (19% identical), ZBED8 (19% identical), THAP12 (12% identical), GTF2IRD1 (10% identical), ZMYM2 (9% identical), ZMYM3 (9% identical), ZMYM4 (9% identical), GTF2I (8% identical), ZMYM6 (8% identical), and 6 more.
Diseases named in the same sentence as EPM2AIP1 in open-access papers:
EPM2AIP1 is named in the same sentence as 9 diseases in open-access papers, as found by Europe PMC text mining. Sharing a sentence is not in itself a finding about the gene and the disease. The quoted sentences say what the papers report.
Insulin resistance (3 papers, 2021 to 2022). Increased resistance towards insulin, that is, diminished effectiveness of insulin in reducing blood glucose levels. "Epm2aip1 (LFMM q-value = 0.002) is involved in glycogen metabolism; inactivation of this gene in laboratory mice causes hepatic insulin resistance and resistance to age-related obesity." (PMID 33914747, 2021). "The absence of Epm2aip1 in mice impaired allosteric activation of glycogen synthesis, decreased hepatic glycogen synthesis, increased liver fat, caused hepatic insulin resistance, and protected against age-related obesity." (PMID 35455641, 2022). "Moreover, the absence of EPM2AIP1 in mice impairs the allosteric activation of GS by glucose 6-phosphate, reduces liver glycogen synthesis, increases liver fat, and promotes liver insulin resistance." (PMID 33668039, 2021).
colon cancer (1 paper, 2025). "In addition, our findings are consistent with evidence from GWAS that genes at locus 3p22.2 (including MLH1 and EPM2AIP1) have proximal colon cancer-specific effects." (PMID 40447568, 2025).
hereditary colorectal cancers (1 paper, 2019). "Interestingly, EPM2AIP1 is part of a bidirectional promotor with MLH1 and epimutations causing hypermethylation has been linked to hereditary colorectal cancers." (PMID 31466397, 2019).
Lafora disease (1 paper, 2022). Lafora disease (LD) is a rare, inherited, severe, progressive myoclonic epilepsy characterized by myoclonus and/or generalized seizures, visual hallucinations (partial occipital seizures), and progressive neurological decline. "EPM2AIP1 plays a crucial role in Lafora disease (LD), a fatal form of progressive myoclonus epilepsy characterized by neurodegeneration and the presence of intracellular polyglucosan inclusions (Lafora bodies) in different tissues." (PMID 35455641, 2022).
cancer (3 papers, 2019 to 2024). A tumor composed of atypical neoplastic, often pleomorphic cells that invade other tissues. "MLH1 and EPM2AIP1 were differentially expressed in all three cancers, RPL22L1 was included in the MAP signature of CRC and STAD, and H2AFJ was observed in both CRC and UCEC." (PMID 35428835, 2022).
EPM2AIP1 also shares sentences with these, for which no sentence is quoted: gastric cancer (1 paper); progressive myoclonus epilepsy (1); rectal cancer (1); uterine cancer (1).